RN7SL167P (RNA, 7SL, cytoplasmic 167, pseudogene)
Gene: Miscellaneous RNA gene on chromosome 11 (131,004,128 to 131,004,429, reverse strand). Ensembl gene ENSG00000242673.
Homologues: Orthologues: chimpanzee Metazoa_SRP (99% identical), macaque Metazoa_SRP (91% identical). Paralogues in human: RN7SL1 (81% identical), RN7SL3 (81% identical), RN7SL2 (80% identical), RN7SL398P (79% identical), RN7SL220P (78% identical), RN7SL296P (78% identical), RN7SL732P (78% identical), RN7SL122P (78% identical), RN7SL126P (78% identical), RN7SL357P (78% identical), RN7SL478P (77% identical), RN7SL479P (77% identical), and 703 more.